NLRP3 (NLR family pyrin domain containing 3)
Diseases named in the same sentence as NLRP3 in open-access papers (continued):
Sharing a sentence is not in itself a finding about the gene and the disease.
acne (continued). "In studies on acne, P. acnes was able to induce the pyroptosis of human sebocytes or monocytes via the NLRP3 signaling pathway." (PMID 33603947, 2021). "Studies suggest that C. acnes can activate the NLRP3 inflammasome pathway, eventually resulting in elevated IL-1β levels and contributing to the pathogenesis of acne." (PMID 33849530, 2021). "In the previous study, researchers have identified that caspase-1, ASC, and NLRP3 knockdown or knockout inhibits P. acnes-induced IL-1β production in acne." (PMID 34603464, 2021). "Auranofin inhibited Propionibacterium acnes-induced activation of the NLRP3 inflammasome in primary mouse macrophages and human sebocytes resulting in a reduction in inflammatory symptoms in a P. acnes-induced mouse acne model." (PMID 33534121, 2021). "Owing to the key role of the NLRP3 inflammasome in the induction of inflammation in acne lesions, it is suggested that its suppression can be critical in the treatment of acne." (PMID 33111746, 2020). "Acne lesions have high levels of IL-1β, which is thought to be a crucial driver of the inflammatory response in acne vulgaris, and is initiated by the activation of the NLRP3 inflammasome." (PMID 33111746, 2020). "NOD-like receptor pyrin domain-containing protein 3 (NLRP3) may be involved in the pathogenesis of acne vulgaris." (PMID 41178942, 2025). "However, further research is needed to evaluate the interaction mechanism between ketones and NLRP3 and determine its efficacy and safety as a treatment option for acne vulgaris." (PMID 41178942, 2025). "Moreover, some previous studies have suggested that the NLRP3 inflammasome ultimately triggers pyroptosis, leading to various skin diseases, including AD and acne." (PMID 37175425, 2023). "Besides, acne induces inflammation by activating the NLRP3 inflammasome through the MAPK/NF-κB signaling pathway." (PMID 36387340, 2022). "Since NLRP3 is the first mediator in the activation of the inflammasome pathway, inhibition of NLRP3 expression may inhibit the next step of the pathway, in which caspase-1 finally activates IL-1β, resulting in the development of acne." (PMID 36624865, 2022). "In light of the potential role of IL-1β in acne pathogenesis, monoclonal anti-IL-1β and/or molecules that could regulate NLRP3, caspase-1, or K+ efflux should be considered in treatments of acne." (PMID 35329904, 2022). "Furthermore, our findings provide a new clue for potential anti‐acne therapy that can work by modulating the activation of the NLRP3 inflammasome induced by P. acnes in the skin." (PMID 35871079, 2022). "NLRP3 is activated in sebocytes by Cutibacterium acnes (previously referred to as Propinibacterium acnes), the prominent member of microbiota, which is thought to be responsible for acne vulgaris formation." (PMID 33925158, 2021). "Hence, targeting the NLRP3 inflammasome and IL-1β could be a potential therapeutic approach for acne." (PMID 39421673, 2024). "Notably, mature caspase-1 and NLRP3 are identifiable around the pilosebaceous follicles and macrophages within acne lesions, thus affirming the potential for C. acnes-mediated NLRP3 activation in acne development." (PMID 37344849, 2023). "Inhibiting NLRP3 and IL-1β expression may also reverse or prevent acne." (PMID 36624865, 2022). "Inhibiting NLRP3 and IL-1β expression may reverse or prevent acne." (PMID 36624865, 2022). "Syndromic HS forms, including Pyoderma gangrenosum, Acne, and Suppurative Hidradenitis (PASH) and Pyogenic Arthritis, Pyoderma gangrenosum, Acne, and Suppurative Hidradenitis (PAPASH) syndromes, involve genetic changes in PSTPIP1, NLRP3, and other autoinflammatory genes." (PMID 40458403, 2025). "Moreover, the prominent induction of genes, such as PTGS2, CXCL8, IL6, IL1B, matrix metalloproteinase 1 (MMP1) and NLRP3, even raised the possibility that EGF and PA may be involved in the pathogenesis of acne." (PMID 34025636, 2021).
acne (continued). "Furthermore, one report found that NLRP3 (NOD-like receptor protein 3) rs10754558, but not rs4612666, was significantly associated with acne risk." (PMID 33849530, 2021).
IgA nephropathy (31 papers, 2013 to 2025). "GTF effectively improves albuminuria in IgA nephropathy mice, and its mechanism is potentially linked to the regulation of NLRP3 expression." (PMID 41210855, 2025). "Emerging evidence indicates that ROS generation, coupled with activation of NF-κB and the NLRP3 inflammasome, constitutes a central pathogenic axis driving the progression of IgA nephropathy." (PMID 41357229, 2025). "Kidney inflammation caused by the NLRP3 inflammasome has also been linked to the advancement of IgA nephropathy." (PMID 35204131, 2022). "Consistent with these in vitro findings, low NLRP3 mRNA expression in renal biopsies correlates with a linearly increased risk of the composite endpoint of serum creatinine doubling and progression to end-stage kidney disease in IgA nephropathy patients." (PMID 41357229, 2025). "The aim of this study was to investigate whether NLRP3 expression associated with podocyte injury was involved in the pathogenesis of IgA nephropathy (IgAN)." (PMID 31796125, 2019). "An expanding body of evidence demonstrates that the NLRP3 inflammasome contributes to the pathogenesis of multiple kidney diseases, including IgA nephropathy." (PMID 41357229, 2025). "Collectively, these data indicate that NLRP3 is predominantly a tubule-expressed protein in the human kidney, and its expression is paradoxically reduced in progressive IgA nephropathy." (PMID 41357229, 2025). "Emerging evidence indicates that IgA1-containing immune complexes directly trigger NLRP3 inflammasome activation in both macrophages and podocytes in IgA nephropathy." (PMID 41357229, 2025). "Targeted inhibition of NLRP3 within the kidney has therefore emerged as a promising therapeutic strategy for IgA nephropathy." (PMID 41357229, 2025). "Compared with control kidneys, renal tissues from patients with IgA nephropathy exhibit significantly elevated NLRP3 gene expression." (PMID 41357229, 2025). "In patients with IgA nephropathy, circulating levels of NLRP3 inflammasome-derived cytokines, notably interleukin-18 (IL-18) and interleukin-1β (IL-1β), are significantly elevated, underscoring the inflammasome’s central role in disease progression." (PMID 41357229, 2025). "Compared with healthy controls, renal tissue from IgA nephropathy patients exhibits significantly elevated NLRP3 inflammasome expression." (PMID 41357229, 2025). "Further investigation needs to be done to clarify the exact role of NLRP3 inflammasome in IgA nephropathy." (PMID 38177104, 2024). "In an IgA nephropathy cell model established by treating human GMCs with IgA1, a study confirmed a significant increase in NLRP3, IL-1β, and IL-18 protein levels." (PMID 38193803, 2024). "In IgA nephropathy mice, IgA immune complexes activate NLRP3 inflammasomes in macrophages, leading to mitochondrial integrity loss and mitochondrial ROS production." (PMID 38740765, 2024). "In mice, both genetic deficit and pharmacological suppression of NLRP3 employing shRNA in a preventive or therapeutic way significantly slowed the development of IgA nephropathy." (PMID 35204131, 2022). "CRNDE interacted with NLRP3 and decreased TRIM31-mediated NLRP3 ubiquitination to activate the NLRP3 inflammasome and exacerbate IgA nephropathy progression." (PMID 36620540, 2022). "Resveratrol, a naturally occurring plant polyphenol compound, has been shown to inhibit the activation of the NLRP3 inflammasome in macrophages by inducing autophagy in a mouse model of progressive IgA nephropathy." (PMID 33854691, 2021). "NLRP3 is expressed in human kidney biopsy specimens and in primary human proximal tubular cells (HPTCs), and its expression levels correlate with clinical outcomes in IgA nephropathy." (PMID 41357229, 2025).
IgA nephropathy (continued). "The activation of the NLRP3 inflammasome in IgA nephropathy is orchestrated through multiple interconnected pathways—including NF-κB signaling, impaired autophagy, mitochondrial reactive oxygen species (mtROS) overproduction, and exosome-mediated intercellular communication." (PMID 41357229, 2025). "It is still unclear whether NLRP3′s inflammasome-independent actions are involved in the pathogenesis of IgA nephropathy." (PMID 35204131, 2022). "Additionally, it has been reported that resveratrol can inhibit the activation of the NLRP3 inflammasome by inducing autophagy, which ameliorates IgA nephropathy." (PMID 35115927, 2021). "Notably, certain traditional Chinese herbal medicines exert renoprotective effects in IgA nephropathy by targeting the NLRP3 inflammasome and its downstream signaling components, thereby modulating inflammatory cytokine production and associated pathways to attenuate disease progression." (PMID 41357229, 2025). "However, whether probiotics can treat IgA nephropathy by inhibiting the NLRP3 signaling pathway is still unclear." (PMID 36038927, 2022). "NLRP3 expression was evaluated in human kidney biopsies, primary renal tubular cells (HPTC) and correlated to disease outcomes in patients with IgA nephropathy (IgAN)." (PMID 27093923, 2016). "In addition, in an in vitro IgA nephropathy model using immunoglobulin A1 (IgA1)-induced glomerular mesangial cells (GMCs), TRIM40 was observed to interact directly with NLRP3 inflammasomes." (PMID 38193803, 2024).
kidney injury (31 papers, 2012 to 2026). Trauma to the kidney. "Calcium flux, mitochondrial damage, and mitophagy dysfunction observed in cisplatin-induced kidney injury have been implicated in the NFκB and NLRP3 inflammasome pathway-mediated release of the pro-inflammatory cytokine IL-1β." (PMID 39169052, 2024). "Given that inflammatory responses and immune imbalances are the root causes of several kidney diseases, this study investigated the potential mechanisms underlying NLRP3 inflammasome activation in As-induced kidney injury." (PMID 37624173, 2023). "Pyroptosis is activated by the NLRP3/caspase-1 axis and has been associated with a large number of kidney injuries and diseases." (PMID 37293812, 2023). "Another study indicated that NLRP3 deficiency afforded a significant renal protective effect against IRI in experimental mice, which could be linked with the inflammasome-independent role of NLRP3 in kidney injury." (PMID 37901251, 2023). "The blockade of persistent and excessive sterile inflammatory responses with specific antagonists of NLRP3 inflammasome could be a promising therapeutic strategy for the prevention or treatment of the adverse outcomes associated with kidney injury." (PMID 31616439, 2019). "The nucleotide-binding oligomerization domain-like pyrin-domain-containing protein 3 (NLRP3) inflammasome is a key regulatory element of pyroptosis, which is engaged in kidney injury." (PMID 40141229, 2025). "It is known that the inflammasome-related protein NOD-, LRR- and pyrin domain-containing protein 3 (NLRP3) is activated in tubule epithelial cells in response to microcrystal-induced kidney injury and is a requirement for collagen deposition." (PMID 38095025, 2024). "While previous studies have reported NF-κB activation in nerve cell injury and diquat-induced kidney injury, the precise function of the NLRP3 inflammasome pathway in DQ-induced renal injury remained unclear." (PMID 39045044, 2024). "In aggregate, these findings indicate that the assembly of the NLRP3 inflammasome complex was induced during kidney injury, and the activation of this pathway was attenuated by PGC-1α." (PMID 35013155, 2022). "Specifically, TOLLIP suppressed TLR2/4-NF-κB signaling to protect against PQ-induced NLRP3 inflammasome activation, thus attenuating kidney injuries." (PMID 35720190, 2022). "The pathogenic roles of the NLRP3 inflammasome have been demonstrated in ischemia-reperfusion injury (IRI), folic acid-induced AKI, rhabdomyolysis-induced kidney injury, and contrast-induced kidney injury." (PMID 35204131, 2022). "This study demonstrated that kidney injury was ameliorated by PGC-1α-induced inactivation of the NLRP3 inflammasome via modulation of mitochondrial viability and dynamics." (PMID 35013155, 2022). "Previous reports found that heme from destroyed red blood cells impaired kidney function, and NLR family pyrin domain containing 3 (NLRP3) inflammasome was augmented in case of kidney injury." (PMID 33783986, 2021). "First, we found oxidative stress-induced upregulation of APA trans-factor FIP1 and further 3′UTR shortening of NLRP3, leading to amplification of multiple pathophysiological effects in kidney injury." (PMID 34011928, 2021). "Previous studies suggested that NF-κB and NLRP3 inflammasome pathways were activated and inflammatory cytokine production was increased in CaOx crystal-induced kidney injury." (PMID 34490303, 2021). "In conclusion, the study demonstrated that EA at BL23 exhibited anti‐HUA and nephroprotective effects by inhibiting both the NLRP3 inflammasome and the IL‐6/JAK/STAT3 signaling pathway, reducing renal inflammation and supporting its therapeutic potential for HUA‐associated kidney injury." (PMID 41278550, 2025). "In addition, downregulation of Cx43 restrained NLRP3-inflammasome activation in LPS-induced kidney injury." (PMID 38347637, 2024). "Thus, our study confirms the participation of the NF-κB/NLRP3 inflammasome axis in the development of DQ-induced kidney injury." (PMID 39045044, 2024).
kidney injury (continued). "Therefore, the protective role of statins in lipid-induced kidney injuries is likely attributed to both inhibiting NLRP3 inflammasome activation and promoting degradation of NLRP3 components." (PMID 35562673, 2022). "NLRP3 inflammasome activation is widely considered to induce pyropotic cell death and has been shown to contribute to the infammatory response of various models of kidney injury." (PMID 31474993, 2019). "The findings of this study unravel the role of PGC-1α in the regulation of the NLRP3 inflammasome signaling via modulating mitochondrial viability and dynamics and also suggest a possible therapeutic potential of PGC-1α for kidney injury." (PMID 35013155, 2022). "In conclusion, we demonstrated the role of PGC-1α in the regulation of the NLRP3 inflammasome activation via modulating mitochondrial dynamics and viability, and TNFAIP3 during kidney injury." (PMID 35013155, 2022). "By reducing urate and lipid levels, the NLRP3 inflammasome activation may be suppressed by the treatment with quercetin and allopurinol to protect STZ-induced kidney injury." (PMID 22701621, 2012). "In our study, the protective effect of statins is at least partially attributed to inhibition of NLRP3 components, however, whether statins prevent lipid-induced kidney injuries through inhibiting ROS was not investigated." (PMID 35562673, 2022). "NLRP3 is a detrimental factor in some models of proteinuric or nonproteinuric kidney injury." (PMID 27014913, 2016). "In LPS‐induced kidney injury, miR‐223 can inhibit the inflammatory response by targeting NLRP320; however, no existing study has demonstrated the function of miR‐223/NLRP3 in RIRI." (PMID 39252576, 2024).
tauopathy (31 papers, 2019 to 2026). Neurodegenerative disorders involving deposition of abnormal tau protein isoforms (tau proteins) in neurons and glial cells in the brain. "NLRP3 inflammasome has been associated with Aβ-induced tauopathy in murine models and was upregulated in the brains of AD patients." (PMID 41571675, 2026). "Deficiency of NLRP3 promotes vascular homeostasis, attenuates tauopathy and improves cognitive function in tau-transgenic mice." (PMID 39539344, 2024). "In conclusion, we demonstrated that administration of felodipine, an LTCC blocker, inhibits tauopathy-mediated microglial activation and neuroinflammation-associated molecular target NLRP3 expression in Tau Tg PS19 mice." (PMID 39223564, 2024). "It was published that tauopathy (Tau hyperphosphorylation) and neurodegeneration (hippocampal atrophy) were decreased in the NLRP3-deficient mice compared with wild type mice, implying its critical role." (PMID 35993019, 2022). "(2019) connected NLRP3 to the pathogenesis of tauopathies, as loss of NLRP3 function reduced tau hyperphosphorylation and aggregation by regulating tau kinases and phosphatases." (PMID 35979366, 2022). "Experiments have shown the role of systemic NLRP3-inflammasome-interleukin-1β-mediated inflammation, which accounts for the pathological formation of neurofibrillary tangles in murine models of tauopathy, and in this manner can cause neurodegenerative disease." (PMID 33573322, 2021). "Together with our findings in tauopathy mice, these observations may suggest that NF-κB/NLRP3-associated neuroinflammation is a “proximal” target for enhancing cognitive function with aging and attenuating neurodegeneration (i.e.)." (PMID 39068433, 2024). "By cross-breeding tau-transgenic mice and Nlrp3-knockout mice, we demonstrated that NLRP3 deficiency reserves cerebral pericytes and vasculature in tau-transgenic mice, which may in turn attenuate tauopathy and improve cognitive function." (PMID 39539344, 2024). "Remarkably, P2rx7 disruption in tauopathy model mice not only reduced the expression of oxidative stress-associated genes but also decreased the conversion of microglia into the InfM state, which is characterized by the expression of Nlrp3, Il1b, and other proinflammatory cytokines." (PMID 40678243, 2025). "In addition, because tauopathy (a key hallmark of AD) is associated with NF-κB/NLRP3 activation and cognitive dysfunction, we also treated 2 month-old male and female rTg4510 mice, a common model of tauopathy based on expression of human P301L tau in the forebrain, using the same approach." (PMID 39068433, 2024). "Antagonizing purinoreceptor (P2 × 7R) to prevent the assembly of an active NLRP3 inflammasome in microglia has been suggested as one of the best approaches to control neuroinflammation caused by microglial activation and has therapeutic potential for treating tauopathies." (PMID 33672982, 2021). "Previous studies suggest that TAU protein is responsible for activating the NLRP3 inflammasome, both in mouse models of tauopathy and in samples from patients with frontotemporal dementia (FTD) caused by TAU alterations." (PMID 41486173, 2026). "Reports implicating the NLRP3 inflammasome in the progression of tauopathy hint at a possible role of IL-1β, since cleavage of pro-IL-1β is downstream of NLRP3 activation." (PMID 41191631, 2025). "The activation of NF-κB and NLRP3 via aging or tauopathy induces the production of many pro-inflammatory cytokines." (PMID 39068433, 2024). "Our findings demonstrate that Nanoligomers specifically formulated to target NF-κB and NLRP3 are safe and well-tolerated, engage their target proteins in the brain, reduce neuroinflammation and improve cognitive function with both aging and tauopathy." (PMID 39068433, 2024). "Loss of Nlrp3 inflammasome function was recently shown to reduce tau hyperphosphorylation and aggregation, identifying an important role of microglia and Nlrp3 inflammasome activation in the pathogenesis of tauopathies." (PMID 38352874, 2024).